CXCL2 (C-X-C motif chemokine ligand 2)
Diseases named in the same sentence as CXCL2 in open-access papers (continued):
Sharing a sentence is not in itself a finding about the gene and the disease.
cancer (continued). "RT-PCR revealed a presence of cDNA in cancer samples only; sequences obtained from the amplicons confirmed to be CXCL2 transcripts which showed a 98% identity with Bos taurus CXCL2 (GenBank accession number: NM_174299.3)." (PMID 26513724, 2015). "Although chemotherapeutic agents kill cancer cells, they induce TNF-α production by endothelial and stromal cells, which upregulates CXCL1 and CXCL2 in cancer cells, amplifying the CXCL1/2-S100A8/9 loop and affecting chemoresistance." (PMID 25165728, 2014). "CXCL2 is often overexpressed in cancer cells, and this expression is believed to contribute both to survival and to the pervasiveness of some cancers." (PMID 23755141, 2013). "Chemokine CXCL2, known for recruiting myeloid cells, was expressed in most cancer cells." (PMID 40883281, 2025). "Interestingly, CXCL2 overexpression was also found to induce the occurrence of ferroptosis in cancer cells." (PMID 40115159, 2024). "CXCL2 was found to induce the occurrence of ferroptosis in cancer cell." (PMID 40115159, 2024). "Notably, one of these clusters exhibited a significant expression of cancer‐promoting genes, encompassing Cdkn1a, Plaur, Ptgs2, Cox17, Lilrb4q, G0s2, Egr1, and Cxcl2." (PMID 39113226, 2024). "Finally, to evaluate the role of CXCL2 in the pro-cancer activity of macrophages, the CXCL2 gene in THP-1 cells was silenced." (PMID 38637499, 2024). "In response to lipid related inflammation, CXCL2 could be upregulated and promote cancer progression." (PMID 39538125, 2024). "Moreover, CXCL2 promotes cancer cell proliferation, migration and interaction with extracellular matrix (ECM) components, facilitating liver and peritoneal metastasis." (PMID 38338661, 2024). "Notably, the effects of CXCL2 on cancer cells were effectively diminished by neutralizing CXCL2 or blocking its receptor, CXCR2." (PMID 37686542, 2023). "The expression levels of CXCL2 varied among various cancers." (PMID 37540227, 2023). "However, it has also been reported that CXCL1 and CXCL2 have bidirectional roles in cancer progression." (PMID 37310469, 2023). "CXCL2 is also a mighty neutrophil chemoattractant and is involved in numerous immune responses comprising wound healing, cancer metastasis, and angiogenesis." (PMID 36466847, 2022). "CXCL2 had been found to act as a biomarker in several types of cancers." (PMID 36281171, 2022). "We performed ELISA to determine whether macrophages affect CXCL1 and CXCL2 secretion in cancer cells." (PMID 36552865, 2022). "Previous studies have revealed that CXCL2 plays a significant role in several types of cancers." (PMID 36281171, 2022). "CXCL2 overexpression was then demonstrated to promote cancer cell chemoresistance in EOC." (PMID 34474677, 2021). "In addition, CXCL1 and CXCL2 play a significant role in boosting cancer cell proliferation and migration; CXCL1 also contributes to stemness and regulating epithelial-mesenchymal transition (EMT)-related processes." (PMID 34659370, 2021). "Cancer- or hypoxia-activated Schwann cells release nociceptive mediators such as IL-6, TNFα, CXCL2, and IL-811,15; these mediators could sensitize primary afferent neurons to cause pain." (PMID 33469141, 2021). "CXCL2 was proved to protect cell apoptosis from cisplatin treatment and maintain cancer cell stemness, which might result in cell chemoresistance phenotype." (PMID 34474677, 2021). "Moreover, CXCL2, a chemokine that contributes to cancer metastasis as well as pro-tumorigenic immunomodulation, is upregulated in our GN25 treated samples." (PMID 33381110, 2020). "Also, the transcriptional expressions of CXCLs family members were correlated with patients' individual cancer stages and nodal metastasis status, especially for CXCL2, CXCL3, CXCL4, CXCL7, CXCL9, CXCL10, CXCL11, and CXCL12." (PMID 32963527, 2020).
cancer (continued). "Transcript levels of soluble factors often linked to cancer-promoting (CP) inflammation, such as IL-6, CXCL1, CXCL2, IL-1β, or G-CSF, were markedly higher in COX-competent compared to COX-deficient tumors, and their expression was unchanged in the absence of NK cells." (PMID 33220234, 2020). "Likewise, we observed that 5-fluorouracil administration induced the expression of G–CSF and neutrophilic chemokines, CXCL1 and CXCL2, in cancer cells, by activating NF-κB pathways." (PMID 32422991, 2020). "A study found CXCL2 role in the resistance of anti-cancer drug, anlotinib, in NSCLC." (PMID 31681566, 2019). "EVs generated by cancer cells promoted the polarization of macrophages to an inflammatory phenotype, characterized by the upregulation of several M1-associated genes (IL-1β, IL-8, CCL2, CXCL2) and the downregulation of MRC1 expression, an M2-related marker." (PMID 28600520, 2017). "An HVJ-E vector containing the CXCL2 gene may be applicable as a novel cancer gene therapy strategy." (PMID 27259252, 2016). "Notably, several of the cytokines whose expression was upregulated in parenchymal cancer cells (e.g. CCL2, CCL7, CXCL1, CXCL2, CXCL5, CCL20) have been implicated in the attraction of immune cells." (PMID 27203741, 2016). "CXCL2, overexpressed in cancer cells, contributes both to cancer cell survival and malignancy." (PMID 24940477, 2014). "In the cancer context, CXCL2 and CXCL5 have displayed pro-angiogenic properties." (PMID 21447198, 2011). "Besides the direct effects on CCL5/CXCL2 3’UTRs it is possible that additional indirect regulatory networks orchestrated by miR-204-5p and miR-199b-5p are at play as already demonstrated in other cancer types." (PMID 36418472, 2023). "However, the functional role of CXCL2 in cancer between the races remained uncharacterized." (PMID 37698493, 2023). "In addition, CXCL2 may be used as a new biomarker for predicting cancer prognosis in specific patients." (PMID 37716978, 2023). "TNF-α expression was observed to upregulate expression of several cancer-associated genes in the epithelial cells which include extracellular matrix (ECM) remodeling genes such as MMP9, PLAU, FN1 and ICAM1, chemokines such as CCL2, CXCL2, CXCL3 and CXCL10 and regulatory genes such as UBD and PTGS2." (PMID 34946170, 2021). "Strikingly, Dkk3‐null cancer cells led to an increase in myCAF gene expression (ACTA2, CTGF, PDGFRB), with concomitant downregulation of inflammatory CAF markers (CXCL12, CXCL2) in PSCs." (PMID 41147409, 2026). "In the VPP cancers, significant increases were observed in CXCL1, CXCL2, GZMB, IL6, CCL13, and CCL19, among others." (PMID 40361362, 2025). "We searched for other potential overlaps and found that CXCL2, LIF, UBE2C, KRT5, ICAM1, and CXCL8 were significantly upregulated in STIC lesions identified in patients with cancer compared with adjacent normal epithelium." (PMID 40689422, 2025). "In agreement with our experimental data and the HMS LINCS analysis, we found that CXCL8 expression is strongly correlated with CXCL1 (R2 = 0.59), followed by CXCL2 (R2 = 0.49) and CXCL3 (R2 = 0.48), across all DepMap cancer cell lines." (PMID 40833805, 2025). "We found that cancer cells, and endothelial cells expressed CCL2 or CXCL2, which recruit macrophages, explaining the dominance of myeloid cells in CNSm." (PMID 40883281, 2025). "Ex vivo, inflammatory molecules released from cancer cells [e.g., IL‐8/CXCL8, granulocyte colony‐stimulating factor (G‐CSF), CXCL1, CXCL2, Cathepsin C, and Toll‐like receptor (TLR) ligands] can induce NETs." (PMID 39865544, 2025). "CXCL2, a small secretory member of the CXC chemokine family, played a critical role in maintaining macrophage infiltration induced by cancer." (PMID 40936936, 2025). "Therapeutic Targets: The involvement of CXCL2 and CXCL16 in cancer progression and metastasis highlights their potential as therapeutic targets." (PMID 39546375, 2024).
cancer (continued). "In pan-cancer CAF atlas, we annotated the CAF subpopulation which highly expressed chemokines (CCL19, CCL21 and CXCL2) as inflammatory CAF (iCAF), likely to the previously reported iCAFs." (PMID 39703515, 2024). "Despite contradictory reports, high CXCL1, CXCL2, CXCL8, CXCR2 levels and accordingly high neutrophil levels correlate with cancer aggressiveness and poor patient survival in general." (PMID 38786066, 2024). "CXCL2/12 expression was negatively whereas CXCL14/17 expression was positively correlated with clinicopathological features of UCEC patients, including cancer stage, patients’ age, weight and menopause status." (PMID 38232115, 2024). "Simultaneously, the enhanced CXCL2-mediated crosstalk between OSCC cells and macrophages plays a vital role in the pro-cancer effect of Fn." (PMID 38637499, 2024). "The CXCL2, CXCL12, and CX3CL1 genes of this signature were shown to be significantly expressed in monocytes and cancer cells, according to scRNA-seq analysis." (PMID 37021054, 2023). "TANs can stimulate the recruitment and activation of T cells in cancer through the production of several mediators, including the chemokines CXCL1, CXCL2, CXCL10, CCL2, and CCL3, respectively." (PMID 37444436, 2023). "PDCD1, TGFB1, CXCL8, CCL3, CCL4, and CCL5 were highly expressed in subTME-IS; CXCL2 and CXCL12 were highly expressed in subTME-ICI, which was consistent among cancer types." (PMID 38002057, 2023). "C-X-C motif chemokine ligand 2 (CXCL2), which belongs to the CXC chemokine family, is a small secreted protein that participates in cancer progression and metastasis, osteoblast differentiation and immune regulation." (PMID 37117173, 2023). "MDSCs are attracted by the expression of CXCL2 in the TME and trigger the enhancement of cancer cell survival." (PMID 35954156, 2022). "The smallest cluster (labeled CXC-1) was enriched for cells expressing CXC motif ligands such as CXCL1, CXCL2, and CXCL8, which are thought to stimulate cancer cell proliferation and migration." (PMID 34611171, 2021). "Combining NPG with HO-1 inhibitor demonstrated down-regulation of genes involved in cancer cell invasion and proliferation (EGR1, CXCL2, AREG, CXCL3, EREG, CD3e, CD3g, CD74, and B2M) as compared to NPG or to control animals." (PMID 34066839, 2021). "Cancer cells expressed high levels of ligands CXCL1, CXCL2, CXCL3, and CXCL8, signaling to the receptors CXCR1 and CXCR2 expressed by neutrophils." (PMID 33953163, 2021). "CXCL10, CXCL8, CXCL2, and CXCL3 can also induce cell growth and proliferation and are putative autocrine or paracrine growth factors in cancer." (PMID 33939688, 2021). "The literature data on MIP-2/CXCL2, also known as GRO-2 (or β), are scanty and confusing concerning its cancer-related up- or downregulation or activity." (PMID 34885960, 2021). "CXCL2, another major cytokine regulated by the presence of EICD, is also well-known to promote cancer progression and metastasis." (PMID 32493324, 2020). "In the case of cancer, IL-8 (as well as CXCL1 or CXCL2) is known to be involved in angiogenesis and the recruitment and activation of immune cells." (PMID 31504643, 2020). "Once educated by cancer cells, BM-MSCs secrete CXCL1, CXCL2, SDF1, IL-6, IL-8, TGFβ and microvesicles containing miRNA, such as miRNA-21 and miRNA-34a, all factors implicated in BC survival, progression and chemo-resistance." (PMID 32850459, 2020). "Another interesting observation was that the unmodified alginate samples contained CXCL1, CXCL2, CXCL12, which are powerful neutrophil chemoattractants that are involved in many immune responses including wound healing, cancer metastasis, and angiogenesis." (PMID 31748525, 2019). "Although several chemokines, such as CCL4, CCL19, CCL21, CXCL2 or CXCL12, were upregulated at the invasive border than cancer centre, expressions of their receptors were very low in PTC, except for CXCL12 receptor." (PMID 28489070, 2017).
cancer (continued). "In our study, expression of proinflammatory chemokines IL-8, CXCL1, CXCL2, and CCL3 was upregulated in the early stages of cancer progression." (PMID 27143385, 2016). "Our data on knockdown and overexpression of SET7/9 demonstrate that SET7/9 suppressed CXCL2, IL-11 and three MMP genes in GC cells, which were shown to promote not only cancer cell motility and invasion but also metastasis." (PMID 26701885, 2016). "Cancer cells overexpressing CXCL1 and CXCL2 attract CD11b(+)Gr1(+) myeloid cells into the tumor and produce chemokines including S100A8/9 that enhance cancer cell survival." (PMID 25562519, 2013). "In experiments comparing CD14-high and CD14-low MB49 cancer cells generated through serial FACS sorting and passaging, CD14-high cells exhibited greater enrichment of neutrophil-recruiting chemokines, such as CXCL1 and CXCL2, than did CD14-low cells." (PMID 41486114, 2026). "In parallel with considerable overproduction of other pro-inflammatory modulators, such as TNFα, IL-2, IL-6, MIG (CXCL9), MIP-1β (CCL4) and MIP-2 (CXCL2), we also detected a significantly lower secretion of IL-10 by tILC2s that contradicted the conventional ILC2 role in cancer." (PMID 38524132, 2024). "SDC4high CSCs exhibited high expression of genes such as KLF6, ATF3, and CXCL2, with Kyoto Encyclopedia of Genes and Genomes (KEGG) enrichment analysis revealing their involvement in TNF signaling, MAPK signaling, apoptosis, and cancer development." (PMID 39107908, 2024). "A deduced expression of CXCL2/12 showed negative correlation with cancer stage, patients’ age, weight and menopause status." (PMID 38232115, 2024). "Interestingly, interaction with BMMs, however, strongly induced neutrophil recruiting chemokines like Cxcl2, Cxcl3, Cxcl5, and Cxcl15 in classical PDAC cells, whereas release remained unchanged (9091) or increased much less (8513) in mesenchymal cancer cells." (PMID 37156840, 2023). "Taking into consideration the cancer development process, the following histaminergic genes stood out: GNA15, HRH1-HRH4, MAOA, WASF2, along with inflammation-related genes: AEBP1, CXCL1, CXCL2, CXCL3, CXCL8, SPHK1, and TNFAIP6." (PMID 36902343, 2023). "The expression level of CXCL2 was not negatively correlated with the count of plasmacytoid DCs in any of the analyzed types of cancer." (PMID 37686093, 2023). "Thus, cancer cells were the main producers of CXCL1, CXCL2, and CXCL8, but cancer cell–intrinsic production of these chemokines was prevented by CALB1 expression." (PMID 37192000, 2023). "The signature genes CXCL2, CXCL12 and CX3CL1 were mainly expressed in cancer cells and monocytes." (PMID 37021054, 2023). "In addition, accumulating research showed that MDSCs have potent mechanisms to promote cancer growth (via downregulation of IFN-γ and expression of MMP9) and metastasis (via TNFα, TGFβ, CXCL2 and S100A8/9) by establishing an immunotolerant environment." (PMID 35211124, 2022). "Thus, C/H treatment modulates the TME by recruiting neutrophils with CXCL2 and polarizes neutrophils into the N1 type via HVJ-E, which activates CTLs against cancer cells." (PMID 33575480, 2021). "These evidences suggest that CXCL1, CXCL2, and CXCL3 may be indirectly involved in the genesis and progression of carcinoma through the mobilization of human immune cells." (PMID 34269159, 2021). "The results indicated that SPP1, TIMP1, and SERPINE1 expression appeared to be remarkably higher in CRC tissues than in the adjacent tissues, while the expression of CXCL2 was not statistically different between cancer tissues and adjacent tissues." (PMID 32936304, 2020). "Our results revealed that CXCL2 was a risk factor for CESC prognosis, which is in line with these previous experimental studies in non-CESC cancers." (PMID 30662454, 2018).
cancer (continued). "NK cells with reduced anti-cancer functions in the immunosuppressive lung tumor microenvironment acquire pro-cancer properties and begin to produce and secrete VEGF and CXCR2 ligands such as CXCL1, CXCL2, and CXCL8/IL-8 as well as IL-6, CCL2, matrix metalloproteinases (MMP), and many others." (PMID 38673949, 2024). "Indeed, after chemotherapy, PD-L2-deficient senescent cancer cells are rapidly eliminated and tumors do not produce the senescence-associated chemokines CXCL1 and CXCL2." (PMID 38267628, 2024). "Together these results indicate that, in 14-3-3ζ+++ cancer cells, low-nutrient- or chemotherapy-induced stresses stabilize NLK protein to induce pS128-Yap1 that releases 14-3-3ζ-bound Yap1 for nuclear translocation and activation, leading to CXCL2/5 upregulation." (PMID 39468013, 2024). "Moreover, expression of CALB1 in cancer cells exhibited a highly significant inverse correlation with cancer cell–intrinsic expression of CXCL1, CXCL2, and CXCL8 and a positive correlation with CCL26 expression, which did not, however, reach statistical significance (P = 0.057)." (PMID 37192000, 2023). "Both the HFD and the cancer cells increased the expression of most genes; however, especially Il1b, Ym1, Cxcl2, Cxcl3, and Cxcr2 were among the most responsive genes to both the HFD and the cancer cells in the PSF which were further exacerbated by the combination of the HFD and cancer cells." (PMID 38264656, 2023). "However, when cocultured, CXCL2 mRNA expression increased in the WT/KLK6−/− BMDMs and cancer cells." (PMID 36552865, 2022). "Interestingly, the genes coding for chemokines such as CXCL1, CXCL2, CXCL3, and CXCL8 (IL-8) were strongly upregulated in CD4+ T cells co-cultured with cancer cells only, further suggesting the direct influence of cancer cells on chemokine expression in CD4+ T cells." (PMID 34439305, 2021). "In addition to these chemokine receptors, chemokine ligands such as CXCL1, CXCL2, CXCL5, CXCL6, CXCL8, and CXCL9 have been also significantly correlated with poor survival and metastasis in several cancers by recruiting MDSCs and suppressing the antitumoral activity of CD8+ T effectors cells." (PMID 32719800, 2020). "However, KLK6 silencing did not affect macrophage-induced CXCL2 production in cancer cells." (PMID 36552865, 2022). "In biopsies lacking CALB1 expression, cancer cells not only transcribed CXCL1, CXCL2, CXCL8, and other immune mediators; they were also the predominant source." (PMID 37192000, 2023). "miR-133a-3p may have a key role in mechanisms that lead to either cancer (target genes CDKN1A, and CCND1) or non-cancerous (target gene EDN1, and CXCL2) conditions secondary to smoking." (PMID 34440025, 2021).